MESD (mesoderm development LRP chaperone)
Description:
Chaperone specifically assisting the folding of beta-propeller/EGF modules within the family of low-density lipoprotein receptors (LDLRs). Acts as a modulator of the Wnt pathway through chaperoning the coreceptors of the canonical Wnt pathway, LRP5 and LRP6, to the plasma membrane. Essential for specification of embryonic polarity and mesoderm induction. Plays an essential role in neuromuscular junction (NMJ) formation by promoting cell-surface expression of LRP4 (By similarity). May regulate phagocytosis of apoptotic retinal pigment epithelium (RPE) cells (By similarity).
Synonyms: KIAA0081; MESDC2; BOCA; OI20
Tractability: Antibody: UniProt predicts a signal peptide or a membrane-spanning region; its Gene Ontology location is reachable by antibodies, with medium confidence. PROTAC: ubiquitination databases record sites on it.
Gene: Protein-coding gene on chromosome 15 (80,946,289 to 80,989,834, reverse strand). Ensembl gene ENSG00000117899.
Subcellular location: Endoplasmic reticulum
Subcellular location (Human Protein Atlas): Endoplasmic reticulum; Cytosol; Nuclear bodies
Gene Ontology:
Molecular function: protein binding; low-density lipoprotein particle receptor binding; identical protein binding; protein folding chaperone
Biological process: ossification; protein folding; mesoderm development; phagocytosis; positive regulation of skeletal muscle acetylcholine-gated channel clustering; protein localization to cell surface; negative regulation of glycoprotein biosynthetic process; positive regulation of Wnt signaling pathway; protein localization to plasma membrane
Cellular component: cytosol; endoplasmic reticulum; nuclear body; plasma membrane
Genetic constraint (gnomAD): Loss-of-function variants: 8 observed, 15.59 expected, observed/expected ratio (o/e) 0.51, 90% interval 0.3 to 0.93. The upper end of that interval is the gene's LOEUF score, 0.93, which puts it in group 3 of 6, group 1 being the genes least tolerant of losing a copy. Missense variants: 342 observed, 308.66 expected, observed/expected ratio (o/e) 1.11, 90% interval 1.01 to 1.21. Synonymous variants: 126 observed, 119.33 expected, observed/expected ratio (o/e) 1.06, 90% interval 0.91 to 1.22.
Homologues: Orthologues: chimpanzee MESD (100% identical), macaque MESD (97% identical), pig MESD (88% identical), dog MESD (87% identical), guinea pig MESD (87% identical), mouse Mesd (84% identical), rabbit MESD (79% identical), rat Mesd (78% identical), tropical clawed frog mesd (66% identical), zebrafish mesd (59% identical), Drosophila melanogaster boca (35% identical), Caenorhabditis elegans bmy-1 (30% identical).
Diseases named in the same sentence as MESD in open-access papers:
MESD is named in the same sentence as 12 diseases in open-access papers, as found by Europe PMC text mining. Sharing a sentence is not in itself a finding about the gene and the disease. The quoted sentences say what the papers report.
COVID-19 (1 paper, 2023). A disease caused by infection with severe acute respiratory syndrome coronavirus 2. "Understanding the biology and functional significance of the four obtained genes (TRMT2A, EXOSC5, REXO2, and MESD) provides insights into the molecular processes associated with disease severity in COVID-19." (PMID 37347079, 2023).
MESD also shares sentences with these, for which no sentence is quoted: cancer (4 papers); adenoma (2); tumor (2); brain cancer (1); breast carcinoma (1); cardiovascular disease (1); CNS tumors (1); inflammatory bowel disease (1); leukemia (1); lung adenocarcinoma (1); lung squamous cell carcinoma (1).